IL4I1 (interleukin 4 induced 1)
Description:
Secreted L-amino-acid oxidase that acts as a key immunoregulator. Has preference for L-aromatic amino acids: converts phenylalanine (Phe), tyrosine (Tyr) and tryptophan (Trp) to phenylpyruvic acid (PP), hydroxyphenylpyruvic acid (HPP), and indole-3-pyruvic acid (I3P), respectively. Also has weak L-arginine oxidase activity. Acts as a negative regulator of anti-tumor immunity by mediating Trp degradation via an indole pyruvate pathway that activates the transcription factor AHR. IL4I1-mediated Trp catabolism generates I3P, giving rise to indole metabolites (indole-3-acetic acid (IAA) and indole-3-aldehyde (I3A)) and kynurenic acid, which act as ligands for AHR, a ligand-activated transcription factor that plays important roles in immunity and cancer. AHR activation by indoles following IL4I1-mediated Trp degradation enhances tumor progression by promoting cancer cell motility and suppressing adaptive immunity. Also has an immunoregulatory function in some immune cells, probably by mediating Trp degradation and promoting downstream AHR activation: inhibits T-cell activation and proliferation, promotes the differentiation of naive CD4(+) T-cells into FOXP3(+) regulatory T-cells (Treg) and regulates the development and function of B-cells. Also regulates M2 macrophage polarization by inhibiting T-cell activation (By similarity). Also has antibacterial properties by inhibiting growth of Gram negative and Gram positive bacteria through the production of NH4(+) and H2O2.
Synonyms: LAAO; LAO; hIL4I1; FIG1
Tractability: Small molecule: it belongs to a druggable protein family. Antibody: UniProt places it where antibodies can reach, with high confidence; its Gene Ontology location is reachable by antibodies, with high confidence; UniProt predicts a signal peptide or a membrane-spanning region. PROTAC: its protein half-life has been measured.
Target class: Enzyme; Oxidoreductase
Gene: Protein-coding gene on chromosome 19 (49,889,654 to 49,929,539, reverse strand). Ensembl gene ENSG00000104951.
Subcellular location: Secreted; Lysosome; Cytoplasmic vesicle, secretory vesicle, acrosome
Subcellular location (Human Protein Atlas): Acrosome; Predicted to be secreted
Pathways (Reactome):
Metabolism: Phenylalanine metabolism
Gene Ontology:
Molecular function: L-amino-acid oxidase activity; L-phenylalaine oxidase activity; protein binding; oxidoreductase activity
Biological process: L-phenylalanine catabolic process; L-tryptophan catabolic process; L-tyrosine catabolic process; negative regulation of T cell activation; negative regulation of T cell mediated immune response to tumor cell; negative regulation of T cell proliferation; positive regulation of regulatory T cell differentiation; positive regulation of transcription by RNA polymerase II; regulation of adaptive immune response; amino acid catabolic process; regulation of B cell differentiation; aromatic amino acid metabolic process
Cellular component: acrosomal vesicle; extracellular region; immunological synapse; sperm midpiece; lysosome; cytoplasm
Genetic constraint (gnomAD): Loss-of-function variants: 23 observed, 28.94 expected, observed/expected ratio (o/e) 0.79, 90% interval 0.57 to 1.13. The upper end of that interval is the gene's LOEUF score, 1.13, which puts it in group 4 of 6, group 1 being the genes least tolerant of losing a copy. Missense variants: 684 observed, 738.68 expected, observed/expected ratio (o/e) 0.93, 90% interval 0.87 to 0.99. Synonymous variants: 371 observed, 324.57 expected, observed/expected ratio (o/e) 1.14, 90% interval 1.05 to 1.25.
Homologues: Orthologues: chimpanzee IL4I1 (98% identical), macaque IL4I1 (96% identical), dog IL4I1 (75% identical), pig IL4I1 (74% identical), guinea pig IL4I1 (73% identical), mouse Il4i1 (72% identical), rat Il4i1 (70% identical), Caenorhabditis elegans spr-5 (19% identical), Caenorhabditis elegans lsd-1 (19% identical), tropical clawed frog maob (17% identical), tropical clawed frog XB5760632 (16% identical), zebrafish mao (16% identical), and 10 more. Paralogues in human: KDM1A (19% identical), MAOB (18% identical), SMOX (18% identical), KDM1B (17% identical), PAOX (17% identical), MAOA (16% identical), PPOX (13% identical).
Diseases named in the same sentence as IL4I1 in open-access papers:
IL4I1 is named in the same sentence as 89 diseases in open-access papers, as found by Europe PMC text mining. Sharing a sentence is not in itself a finding about the gene and the disease. The quoted sentences say what the papers report.
glioma (18 papers, 2018 to 2025). A benign or malignant brain and spinal cord tumor that arises from glial cells (astrocytes, oligodendrocytes, ependymal cells). "Previous studies have shown that IL4I1 is associated with adverse outcomes in some human cancers (e.g., breast cancer, renal cell carcinoma, and glioma)." (PMID 38691253, 2024). "Enrichment analyses in glioma patients suggested that IL4I1 was linked to cytokine and immune responses, and was positively correlated with ICs." (PMID 38250074, 2023). "To delve into the underlying role of IL4I1 in glioma, we assessed its expression across various cell types within the glioma microenvironment, including immune cells, stromal cells, and malignant cells." (PMID 38250074, 2023). "Specifically, IL4I1 was implicated in aggressive progression and a dismal prognosis for patients with glioma." (PMID 38250074, 2023). "In addition, we examined the association between IL4I1 expression and clinical characters in glioma using the CGGA dataset." (PMID 38250074, 2023). "IL4I1 promotes tumor cell movement and inhibits T cell proliferation; these effects are negatively correlated with the OS rate of patients with glioma." (PMID 38691253, 2024). "More recently, reduced methylation of the promoter of IL4I1 was demonstrated to be correlated with aggressive progression and a dismal prognosis for patients with glioma." (PMID 39516356, 2024). "Our study found that the expression level of IL4I1 in gliomas was significantly higher than that in normal brain tissue." (PMID 38691253, 2024). "In patients, DNA methylation was suggested to control the expression of interleukin-4-induced-1 (IL4I1, L-phenylalanine oxidase) in M2-like TAMs in human glioma." (PMID 39516356, 2024). "In the present study, we demonstrated upregulation of IL4I1 expression across 22 tumor types through pan-cancer analysis, with notably elevated levels in glioma." (PMID 38250074, 2023). "In this research, we wish to identify the importance of IL4I1 and its potential as a prognostic and immunotherapeutic biomarker in glioma." (PMID 38250074, 2023). "The combination of immune checkpoint blockade (ICB) and IL4I1 inhibitors is expected to play a therapeutic role in solid tumors such as renal cancer and glioma." (PMID 36866272, 2023). "We demonstrated that knock down of IL4I1 expression in M2-like macrophages resulted in a reduction in the migration and invasion capabilities of co-cultured glioma cells." (PMID 38250074, 2023). "We also identified a positive relation between IL4I1 and macrophages in glioma from the algorithms of TIMER, XCELL, and EPIC." (PMID 38250074, 2023). "The link between IL4I1 levels and the prognosis, methylation, and immune checkpoints (ICs) in gliomas were explored through Kaplan–Meier curve, Cox regression, and Spearman correlation analyses." (PMID 38250074, 2023). "In summary, IL4I1 expression exhibits an escalating pattern with glioma progression, suggesting its potential involvement in the malignant progression of glioma." (PMID 38250074, 2023). "Taken together, the results suggested that IL4I1 was related to more aggressive biologic processes within glioma as other solid and hematologic malignancies." (PMID 38250074, 2023). "The expression levels of risk factors IL4I1, SMS, and ADI1 in high-grade gliomas were higher than those in lower‐grade gliomas, while the protein expression levels of protective factor GCLC, MSRB2, MTAP and MPST were exactly the opposite." (PMID 38057821, 2023). "IL4I1 emerges as a promising immunotherapy target for modulating TAMs selectively and stands as a novel macrophage-related prognostic biomarker in glioma." (PMID 38250074, 2023). "Subsequent assessment of IL4I1 expression in various macrophage subtypes (M0, M1, and M2) and glioma cells (U87, LN229, and U251) revealed that IL4I1 was expressed primarily in macrophages, particularly in the M2 subtype." (PMID 38250074, 2023).
glioma (continued). "In order to explain the biological functions of IL4I1 in glioma, we conducted an analysis of DEGs from the CGGA dataset." (PMID 38250074, 2023). "In a word, our findings indicate that M2-like macrophages in the TME of glioma exhibit notably substantial expression of IL4I1." (PMID 38250074, 2023). "Co-culture models between glioma cells and M2-like macrophages were used to explore the IL4I1-mediated effects on tumor growth, invasion, and migration of glioma cells." (PMID 38250074, 2023). "Results of single-cell analysis highlighted that IL4I1 was expressed predominantly in macrophages, and there was a positive correlation between IL4I1 and macrophages in glioma as indicated by TIMER, XCELL, and EPIC algorithms." (PMID 38250074, 2023). "After elucidating the prognostic relevance of IL4I1, we further investigated the correlation between IL4I1 and tumor progression in glioma." (PMID 38250074, 2023). "This insight undoubtedly offers a more comprehensive and in-depth understanding, building upon previous studies regarding the regulatory role of IL4I1 in glioma progression." (PMID 38250074, 2023). "In the following study, we delve deeper to comprehensively investigate the importance of IL4I1 expression, with a specific focus on gliomas." (PMID 38250074, 2023). "To confirm these data, we investigated the prognostic significance of IL4I1 in three additional independent glioma datasets." (PMID 38250074, 2023). "Nonetheless, there are few systematic and comprehensive studies about the role of IL4I1, especially in the connection between TAMs and the glioma microenvironment." (PMID 38250074, 2023). "Deeper analysis displayed that IL4I1 was positively correlated with the markers of M2-like macrophages, and IF staining between CD206 and IL4I1 confirmed that IL4I1 was substantially co-expressed with TAMs in clinical glioma specimens." (PMID 38250074, 2023). "We analyzed differentially methylated CpG islands located in the promoter regions of IL4I1 in glioma using the MethSurv database." (PMID 38250074, 2023). "Herein, we showed a significant upregulation of IL4I1 expression in glioma tissue than that in normal tissue at both transcriptional and protein levels." (PMID 38250074, 2023). "Collectively, our results show that IL4I1 expression in M2-like macrophages plays crucial roles in aggressive progression of human glioma cell lines." (PMID 38250074, 2023). "In the present study, we found that IL4I1 was closely involved in immune-related function with TAMs in glioma." (PMID 38250074, 2023). "Our IHC results were consistent with the data from TCGA and GTEx databases, demonstrating enrichment of IL4I1 in glioma tissues relative to that in normal tissues." (PMID 38250074, 2023). "Meanwhile, researchers found that the ectopic expression of IL4I1 on glioma cells can promote their migration ability." (PMID 38250074, 2023). "Among them, the expression of IL4I1 in glioma patients was greater than of normal samples, while the CYP1A1, OGDHL, and ASMT were lower in glioma samples." (PMID 36407768, 2022). "IL4I1 promotes glioma cell migration via the Kyn/AHR pathway, and suppresses T cell proliferation in glioblastoma, which is associated with poor survival of glioma patients." (PMID 34659216, 2021). "IL4I1 is a metabolic, immune checkpoint that activates the aryl hydrocarbon receptor and promotes glioma progression." (PMID 34917513, 2021). "Further, the IL4I1 protein level in patient serum and the glioma TME will also be detected." (PMID 40071723, 2025). "However, among the three TCEs, only the mRNA level of IL4I1 was closely related to prognosis in patients with gliomas and mesenchymal type GBM." (PMID 40071723, 2025). "We first verified the IL4I1 mRNA and protein levels in patients with different glioma grades." (PMID 40071723, 2025). "Previous studies have shown that IL4I1 is highly expressed in gliomas." (PMID 38691253, 2024). "This suggests that IL4I1 is a potential target for glioma treatment." (PMID 38691253, 2024).
glioma (continued). "Studies have shown that the overexpression of IL4I1 is related to poor survival in glioma patients." (PMID 36925967, 2023). "Furthermore, TCGA results indicated a connection between IL4I1 expression and a dismal prognosis in glioma patients." (PMID 38250074, 2023). "Furthermore, we constructed a co-culture model to investigate the direct effects of M2-like macrophage-intrinsic IL4I1 in glioma cell response and used CM derived from siIL4I1-treated M2-like macrophages to stimulate glioma cells." (PMID 38250074, 2023). "Our findings also indicated that high expression of IL4I1 elicited a malignant phenotype of glioma." (PMID 38250074, 2023). "Collectively, these findings implicate that the immunological role of IL4I1 in glioma might be attributed to the TME where TAMs exhibit heightened IL4I1 expression." (PMID 38250074, 2023). "Clinical information of glioma patients in the CGGA dataset according to IL4I1 expression levels." (PMID 38250074, 2023). "Moreover, IL4I1 accelerated the polarization of the M2-like macrophages and induced the invasion and migration of co-cultured glioma cells." (PMID 38250074, 2023). "Importantly, co-culture models proved that IL4I1 significantly promoted the invasion and migration of glioma cells, and induced the polarization of M2-like macrophages." (PMID 38250074, 2023). "Meanwhile, by using Cox regression analysis combined with KM survival analysis in three glioma datasets, we proved that IL4I1 could be regarded as an independent prognostic indicator in glioma." (PMID 38250074, 2023). "These outcomes underscore the critical role of IL4I1 in immune-related functions in glioma." (PMID 38250074, 2023). "However, utilizing IL4I1CX3CR1KO mice models for glioma would allow for more comprehensive exploration of IL4I1 patterns and functions between M2-like macrophages and other immune cell subsets and ICs." (PMID 38250074, 2023). "Furthermore, upon conducting single-cell analysis on gliomas, it was observed that IL4I1 expression was localized predominantly in macrophages." (PMID 38250074, 2023). "In addition, stable silencing of IL4I1 expression in M2-like macrophages significantly hampered the migration and invasion of glioma cells, as observed in transwell assays." (PMID 38250074, 2023). "A recent study has pointed out that instead of IDO1, interleukin 4 induced 1 (IL4I1) is the novel and the main Trp‐catabolic enzyme in glioma and chronic lymphocytic leukemia, which explains the major reason why the clinical trials of IDO1 inhibitors are a failure." (PMID 37655051, 2023). "In addition, studies have shown that Interleukin 4-inducible-1 (IL4I1), another enzyme in the tryptophan metabolism, is negatively correlated with the overall survival (OS) of glioma patients." (PMID 36925967, 2023). "With a specific focus on glioma, we delved into the correlation between IL4I1 expression and the malignant progression of glioma by multiple forms of bioinformatics analysis: prognostic value, malignant progression, DNA methylation, single-cell transcriptome, and immune functions." (PMID 38250074, 2023). "IL4I1 could be a promising immunotherapy target for selective modulation of TAMs and stands as a novel macrophage-related prognostic biomarker in glioma." (PMID 38250074, 2023). "Furthermore, K-M analysis showed that compared with patients with IL4I1 hypermethylation, hypomethylation experienced a worse prognosis in glioma patients." (PMID 38250074, 2023). "Furthermore, IF staining targeting CD206 (prominent marker of M2-like macrophages), in conjunction with IL4I1 reaffirmed substantial co-expression of IL4I1 with TAMs in clinical glioma specimens." (PMID 38250074, 2023). "However, there is limited understanding of the IL4I1-mediated cross-talk function between TAMs and glioma cell in the glioma microenvironment." (PMID 38250074, 2023).